EXD3 (exonuclease 3'-5' domain containing 3)
Description:
Possesses 3'-5' exoribonuclease activity. Required for 3'-end trimming of AGO1-bound miRNAs (By similarity).
Synonyms: LOC54932; FLJ20433; mut-7; Nbr
Tractability: No criterion of Open Targets' tractability assessment is met for any kind of drug.
Gene: Protein-coding gene on chromosome 9 (137,306,894 to 137,423,260, reverse strand). Ensembl gene ENSG00000187609.
Subcellular location (Human Protein Atlas): Focal adhesion sites; Actin filaments
Gene Ontology:
Molecular function: protein binding; 3'-5' exonuclease activity; nucleic acid binding
Genetic constraint (gnomAD): Loss-of-function variants: 84 observed, 73.33 expected, observed/expected ratio (o/e) 1.15, 90% interval 0.96 to 1.37. The synonymous counts are far from expectation, so gnomAD's model fits this gene poorly and the ratio says little. Missense variants: 1,197 observed, 1,013.1 expected, observed/expected ratio (o/e) 1.18, 90% interval 1.13 to 1.24. Synonymous variants: 556 observed, 448.13 expected, observed/expected ratio (o/e) 1.24, 90% interval 1.16 to 1.33.
Homologues: Orthologues: macaque EXD3 (91% identical), pig EXD3 (67% identical), dog EXD3 (66% identical), zebrafish exd3 (38% identical), tropical clawed frog exd3 (36% identical), Caenorhabditis elegans mut-7 (18% identical), Drosophila melanogaster Nbr (14% identical), Caenorhabditis elegans ZK1098.3 (14% identical). Paralogues in human: EXD2 (13% identical).
Diseases named in the same sentence as EXD3 in open-access papers:
EXD3 is named in the same sentence as 10 diseases in open-access papers, as found by Europe PMC text mining. Sharing a sentence is not in itself a finding about the gene and the disease. The quoted sentences say what the papers report.
insomnia (2 papers, 2023 to 2025). A sleep disorder characterized by difficulty in falling asleep and/or remaining asleep. "We observed that all variants that were discovered associating with RLS showed high posterior probability (>0.8) of being uniquely associated with RLS, with one signal at EXD3 locus shared between clinical insomnia and RLS (PP = 1)." (PMID 41332830, 2025). "Importantly, a GWAS of PTSD in the MVP also detected an association with EXD3 and our lead GWS SNP (rs77641763) in EXD3 has been previously associated with chronotype (“morningness”) and insomnia." (PMID 36940203, 2023). "But despite these connections to PTSD and insomnia, EXD3 was the only SI locus that remained GWS when conditioned on comorbid conditions, albeit the SNP was not present in the PTSD GWAS." (PMID 36940203, 2023).
Anxiety (1 paper, 2023). Intense feelings of nervousness, tension, or panic often arise in response to interpersonal stresses. "Anxiety brain correlates are moderated by variations in the exonuclease EXD3 gene, which is involved in nucleic acid binding with the highest expression in frontal cortical areas." (PMID 37322117, 2023). "The lead SNP in the GWAS of the anxiety symptom group was rs77641763, which is located in intron 15 of the EXD3 gene of chromosome 9 (P = 9.53 × 10−11) (, g)." (PMID 37322117, 2023). "The EXD3 gene score (EME = 1.65%) moderated the mediation pathway of the anxiety symptom group and the IFT74 gene score (EME = 1.52%) moderated the mediation pathway of the emotional instability symptom group." (PMID 37322117, 2023). "Participants with lower EXD3 gene scores showed smaller correlation of the urban environmental profile with the anxiety symptom group compared to those with higher EXD3 gene scores (z = −2.61, P = 0.009)." (PMID 37322117, 2023). "Protective factors such as greenness and generous destination accessibility were negatively correlated with an anxiety symptom group (r = 0.10, Pperm < 0.001), mediated by brain regions necessary for emotion regulation and moderated by EXD3, explaining 1.65% of the variance." (PMID 37322117, 2023). "Of the 11 gene scores in the anxiety symptom group, we replicated six genes, including CNNM2, EXD3, GBF1, NT5C2, NOLC1 and TRIM." (PMID 37322117, 2023).
fibromyalgia (1 paper, 2023). A chronic disorder of unknown etiology characterized by pain, stiffness, and tenderness in the muscles of neck, shoulders, back, hips, arms, and legs. "Several genes/loci have been reported more than once in CWP, fibromyalgia, and MCP, including EXD3, SLC39A8, AMIGO3/GMPPB/RNF123, C6orf106, FAF1, SLC24A3, and LINC01065/LINC00558." (PMID 37144689, 2023).
glioma (1 paper, 2024). A benign or malignant brain and spinal cord tumor that arises from glial cells (astrocytes, oligodendrocytes, ependymal cells). "Furthermore, we could identify several novel glioma biomarkers likely helpful in both diagnosis and prognosis of the patients, including the genes PPP1R8, GPBP1L1, KIAA1614, C14orf23, CCDC77, BVES, EXD3, CD300A, and HEPN1." (PMID 38812741, 2024).
ovarian carcinoma (1 paper, 2014). A malignant neoplasm originating from the surface ovarian epithelium. "The gene ‘EXD3’ is within these 241 overlapping genes, which are associated with some molecular and cellular functions related to ovarian cancer, such as carcinogenesis, cell cycle regulation and apoptosis." (PMID 24392133, 2014).
cancer (1 paper, 2021). A tumor composed of atypical neoplastic, often pleomorphic cells that invade other tissues. "Since K69 and K285 residues are known regulatory switches for DVL-1 nuclear localization, we wanted to determine whether these K-residues on DVL-1 also influence transcript levels of DVL-1 target genes such as TRIO, COL5A1 and EXD3 implicated in cancer." (PMID 34659647, 2021). "Using the ChIP Seq bam files, we visualized the exact genomic location of DVL-1 binding (blue peak) at various cancer-associated genes not previously designated as Wnt target genes such as TRIO, COL5A1, EXD3, OR4A47, GLDN, and EFCAB6 compared to IgG control (red peak) using IGV." (PMID 34659647, 2021).
EXD3 also shares sentences with these, for which no sentence is quoted: diabetic kidney disease (1 paper); emotional instability (1); infection (1); phobia (1).